RBM14 (RNA binding motif protein 14)
Description:
Isoform 1 may function as a nuclear receptor coactivator, enhancing transcription through other coactivators such as NCOA6 and CITED1. Isoform 2, functions as a transcriptional repressor, modulating transcriptional activities of coactivators including isoform 1, NCOA6 and CITED1. Regulates centriole biogenesis by suppressing the formation of aberrant centriolar protein complexes in the cytoplasm and thus preserving mitotic spindle integrity. Prevents the formation of the STIL-CPAP complex (which can induce the formation of aberrant centriolar protein complexes) by interfering with the interaction of STIL with CPAP. Plays a role in the regulation of DNA virus-mediated innate immune response by assembling into the HDP-RNP complex, a complex that serves as a platform for IRF3 phosphorylation and subsequent innate immune response activation through the cGAS-STING pathway. Also involved in the regulation of pre-mRNA alternative splicing.
Synonyms: PSP2; SIP; SYTIP1; COAA; DKFZp779J0927; TMEM137
Tractability: PROTAC: UniProt records ubiquitination sites on it; ubiquitination databases record sites on it; its protein half-life has been measured.
Gene: Protein-coding gene on chromosome 11 (66,616,626 to 66,629,934, forward strand). Ensembl gene ENSG00000239306.
Subcellular location: Nucleus; Nucleus, nucleolus; Cytoplasm
Subcellular location (Human Protein Atlas): Nucleoplasm; Cytosol; Nuclear speckles
Pathways (Reactome):
Gene expression (Transcription): RUNX2 regulates bone development
Gene Ontology:
Molecular function: protein binding; RNA binding; transcription coactivator activity; mRNA binding; nucleic acid binding; splicing factor binding
Biological process: activation of innate immune response; centriole assembly; negative regulation of centriole replication; positive regulation of transcription by RNA polymerase II; transcription initiation-coupled chromatin remodeling; regulation of alternative mRNA splicing, via spliceosome; response to hormone; gene expression; mRNA splicing, via spliceosome
Cellular component: cytoplasm; cytosol; nuclear speck; nucleoplasm; nucleus; transcription regulator complex; ribonucleoprotein complex; nucleolus
Genetic constraint (gnomAD): Loss-of-function variants: 5 observed, 53.68 expected, observed/expected ratio (o/e) 0.0932, 90% interval 0.048 to 0.2. The upper end of that interval is the gene's LOEUF score, 0.2, which puts it in group 1 of 6, group 1 being the genes least tolerant of losing a copy. Missense variants: 780 observed, 954.97 expected, observed/expected ratio (o/e) 0.82, 90% interval 0.77 to 0.87. Synonymous variants: 411 observed, 422.02 expected, observed/expected ratio (o/e) 0.97, 90% interval 0.9 to 1.06.
Homologues: Orthologues: macaque RBM14 (100% identical), chimpanzee RBM4 (99% identical), dog RBM14 (99% identical), guinea pig RBM14 (99% identical), pig RBM14 (99% identical), rat Rbm14 (99% identical), mouse Rbm14 (98% identical), tropical clawed frog rbm14 (32% identical), zebrafish rbm14b (24% identical), zebrafish rbm14a (19% identical). Paralogues in human: SF3B4 (11% identical), ELAVL2 (11% identical), HNRNPR (11% identical), ELAVL4 (10% identical), ELAVL3 (10% identical), PABPC1 (10% identical), SYNCRIP (10% identical), PABPC3 (10% identical), ELAVL1 (9% identical), PABPC4 (9% identical), RBMS3 (9% identical), PABPC1L (9% identical), and 12 more.
Diseases named in the same sentence as RBM14 in open-access papers:
RBM14 is named in the same sentence as 24 diseases in open-access papers, as found by Europe PMC text mining. Sharing a sentence is not in itself a finding about the gene and the disease. The quoted sentences say what the papers report.
glioblastoma (6 papers, 2014 to 2025). The most malignant astrocytic tumor (WHO grade IV). "RBM14 has been implicated in the migration of breast cancer, heightened radio-resistance in glioblastoma, and more recently, promoting cell growth in lung cancer." (PMID 38745208, 2024). "We originally identified RBM14 as a gene that radio-sensitizes glioblastoma multiforme (GBM) spheres when knocked down." (PMID 26927092, 2016). "In addition, RBM14 has been implicated in DNA repair by c-NHEJ49,68, and its knock-out sensitizes glioblastoma cells to radiotherapy." (PMID 39870664, 2025). "Afterwards, RBM14 KD was found to significantly influence the kinetics of DSBs repair and reduce DNA-PKcs phosphorylation in glioblastoma multiforme (GBM), without affecting the expression level of total DNA-PKcs, and sensitizing radio-resistant GBM cells in vivo." (PMID 32630183, 2020).
lung carcinoma (4 papers, 2023 to 2025). "In summary, these results revealed that DNA methylation or YY1-EP300-mediated histone modification activates RBM14 transcription, which is implicated in the reprogramming of glycolysis in lung cancer." (PMID 37060064, 2023). "Similarly, RBM14 has been linked to the reprogramming of glycolysis in lung cancer, acting as a novel epigenetically activated oncogene." (PMID 41277807, 2025). "For instance, O‐GlcNAcylation at Ser521 of the nuclear receptor coactivator RBM14 enhances its transcriptional activity, promoting the proliferation and metastasis of lung cancer cells." (PMID 41394960, 2025). "Moreover, the treatment of 5-aza-dC, an inhibitor for DNA methylation, slightly upregulated the level of RBM14 mRNA in four lung cancer cell lines, indicating that the expression of RBM14 was regulated by DNA methylation." (PMID 37060064, 2023). "Besides, the mRNA and protein levels of RBM14 were significantly enhanced in lung cancer cell lines when compared with its levels in HBE cells." (PMID 37060064, 2023). "Here, we focused on exploring the function of RBM14 in lung cancer." (PMID 37060064, 2023). "There are only several studies suggesting that overexpression and deletion of RBM14 gene may be involved in tumorigenesis and progression, but the function and regulation mechanism of RBM14 in lung cancer remains unknown." (PMID 37060064, 2023). "Our result suggested that RBM14 can be a potential therapeutic target for lung cancer." (PMID 37060064, 2023). "However, the expression and biological role of RBM14 in lung cancer remain unclear." (PMID 37060064, 2023). "However, the effect of RBM14 on lung cancer remains unclear." (PMID 37060064, 2023). "Here, we found that the DNA methylation levels of RBM14 promoter are decreased in LUAD and 5-aza-dC treatment promoted the expression of RBM14 in lung cancer cell lines, indicating that DNA methylation of RBM14 is one of the induction factors for the overexpressed RBM14 in LUAD." (PMID 37060064, 2023).
viral infection (3 papers, 2018 to 2025). "In the context of viral infection, RBM14 RNA processing functions are important for latent viral gene expression for both HIV and Epstein-Barr virus, and its function was also shown to support influenza replication." (PMID 39772686, 2025). "RBM14 has also been found to interact with TRAF3 in immunocomplexes that arise in response to dsDNA and dsRNA sensors, further suggesting a role in the innate immune response to viral infection." (PMID 30429226, 2018). "Additionally, RBM14 is an indirect coactivator of gene expression and as such its effects on gene expression may be modulated either by the host (in response to viral infection) or by the virus itself in an effort to subvert antiviral responses or to rewire the response to support virus replication." (PMID 30429226, 2018).
breast carcinoma (2 papers, 2024 to 2025). "To this end, we induced DNA damage in our set of RBM14- vs. luciferase-overexpressing lung and breast cancer cell lines and treated with the STAT3 inhibitors C188-9 and HJC052 for 72 h." (PMID 39870664, 2025). "We validate RBM14 as an ARGOS gene in lung and breast cancer cells, and suggest a toxicity mechanism involving altered DNA damage response and STING signaling." (PMID 39870664, 2025). "Altogether, these results show that low-level overexpression of RBM14 negatively impacts cellular proliferation and viability in our lung and breast cancer models, regardless of gene amplification status." (PMID 39870664, 2025).
lung adenocarcinoma (2 papers, 2023 to 2025). A carcinoma that arises from the lung and is characterized by the presence of malignant glandular epithelial cells. "RBM14 level is increased in lung adenocarcinoma (LUAD) cells." (PMID 37060064, 2023).
pancreatic cancer (2 papers, 2021 to 2022). "A total of 8 immune genes (ITGA7, RBM14, DENND4B, LQK1, ZNF709, COL7A1, SP1, NCBP2) were identified as independent prognostic factors of pancreatic cancer, which were used to construct a clinical predictive model." (PMID 33546693, 2021). "We aimed to explore the role of Solute Carrier Family 35 Member F2 (SLC35F2) in pancreatic cancer (PCa) and to further study whether SLC35F2 regulates cisplatin resistance of PCa cells through the modulation of RNA binding motif protein 14 (RBM14) expression." (PMID 35669242, 2022). "However, NCBP2, RBM14, LQK1, and ZNF709 have not been reported to be related to pancreatic cancer." (PMID 33546693, 2021).
colorectal cancer (1 paper, 2025). A primary or metastatic malignant neoplasm that affects the colon or rectum. "We experimentally show that the gain of one of these genes, RBM14, indeed perturbs the DNA damage response and cGAS/STING signaling, and its amplification is associated with increased vulnerability of tumors to radiation treatment in a clinical colorectal cancer cohort." (PMID 39870664, 2025).
glioma (1 paper, 2019). A benign or malignant brain and spinal cord tumor that arises from glial cells (astrocytes, oligodendrocytes, ependymal cells). "RBM14 controls nonhomologous end-joining (NHEJ) DNA repair and knockdown of RBM14 sensitizes glioma spheroids to radiation." (PMID 30644073, 2019).
intestinal inflammation (1 paper, 2022). "Elucidation of the relationship between the composition of gut microbiota and RBM14 expression in IECs and identification of bacteria that induce RBM14 expression will be important for application of microbiota intervention approaches to control diseases involving intestinal inflammation." (PMID 36339704, 2022).
osteosarcoma (1 paper, 2023). A usually aggressive malignant bone-forming mesenchymal neoplasm, predominantly affecting adolescents and young adults. "The overexpression of RBM14 in NIH 3T3 cells promotes cell proliferation and colony formation, whereas the downregulation of RBM14 inhibits osteosarcoma cell growth." (PMID 37060064, 2023).
cancer (8 papers, 2022 to 2025). A tumor composed of atypical neoplastic, often pleomorphic cells that invade other tissues. "Identification of all biological processes associated with RBM14 overexpression, as well as their relative contribution, will require further investigation in additional cancer cell line models as well as in vivo experiments." (PMID 39870664, 2025). "We additionally observe increased patient survival in a radiation-treated cancer cohort with RBM14 amplification." (PMID 39870664, 2025). "Our analysis showed strong gene compensation across cancer types, and ORF screens pointed to RBM14 overexpression also leading to detrimental effects on cell proliferation in multiple cancer types." (PMID 39870664, 2025). "Whereas a strong toxicity and compensation profile could be expected for the tumor suppressor and cell cycle regulator CDKN1A, the effects of RBM14 overexpression on cancer cell growth are novel." (PMID 39870664, 2025). "RBM14, also known as the RRM containing coactivator activator (CoAA), is highly expressed in early embryonic stem cells and has been implicated in DNA repair and cell proliferation in cancer cells." (PMID 35563044, 2022). "Intersecting the sets of pan-cancer compensated and toxic genes yields nine high-confidence ARGOS genes, six of which are also frequently amplified: RBM12, RBM14, SNRPA, ZBTB14, POU2F1, and CDKN1A." (PMID 39870664, 2025). "RBM14 is known to physically interact with PARP1, which is a key player in the DNA damage response (DDR) network and a target of cancer therapy." (PMID 38745208, 2024). "To determine whether RBM14-dependent activation of STING can also elicit non-cell-autonomous immune responses, we finally performed co-culture experiments with our cancer cell line pairs and natural killer (NK) cells." (PMID 39870664, 2025).
tumor (6 papers, 2014 to 2025). "In comparison with adjacent tissues, tumor tissue samples showed an increased expression of RBM14, which was positively correlated with RBM14 expression." (PMID 35669242, 2022). "By analyzing the association between RBM14 expression and EP300 and YY1 levels using TIMER database, we found that RBM14 expression was strongly associated with the expression of EP300, CBP, and CTCF in various types of tumor tissues." (PMID 37060064, 2023). "On the other hand, RBM14 was overexpressed in patients with tumor-free status (P < .05)." (PMID 36401386, 2022). "Besides, RBM14 can play the part of tumor suppressor by reducing the expression of c-Myc." (PMID 37060064, 2023). "In sum, our results show how RBM14 overexpression promotes STING activation in the context of DNA damage, and how this effect impairs immunosuppressive STAT3 signaling and may enhance NK cell-mediated tumor recognition and killing." (PMID 39870664, 2025).
infection (4 papers, 2018 to 2025). The state of being infected such as from the introduction of a foreign agent such as serum, vaccine, antigenic substance or organism. "Although the effect on the high MOI infection was minimal for all tested constructs, a clear proviral role was seen upon expression of WT RBM14 for the low MOI experiment." (PMID 39772686, 2025). "A complex subunit displaying some of the highest increases in lactylation throughout infection was RBM14." (PMID 39772686, 2025). "Given that this effect was specifically evident for the low MOI infection, this result suggests that RBM14 lactyl-like modification at K600 supports virus spread rather than virus replication in the infected cell." (PMID 39772686, 2025). "RBM14 K600 and IFI16 K90 lactylation both promote virus spread by subverting host immunity, a feature that is shared during infection with HSV-1." (PMID 39772686, 2025). "A549 cells were infected with WSN at a multiplicity of infection (MOI) of 1.0 for 24 h, and the cells were then fixed and immunostained with anti-NP and anti-RBM14 antibodies for analysis by wide-field immunofluorescence microscopy." (PMID 30429226, 2018). "Here we report that RBM14 is required for efficient IAV replication and that it relocalizes to the nucleolus upon infection with IAV." (PMID 30429226, 2018). "Given the NS1-driven relocalization of RBM14 and the well-characterized role of NS1 in suppression of innate immune responses to infection, it is conceivable that IAV NS1 may modulate any potential antiviral transcriptional effects of RBM14." (PMID 30429226, 2018). "Furthermore, infection with ΔNS1 PR/8 virus failed to elicit relocalization of RBM14." (PMID 30429226, 2018). "The NS1 proteins of WSN and Pan/99 localize to the nucleolus (to differing degrees) during infection and the NS1 protein of PR/8 does not—yet all of these viruses elicit RBM14 nucleolar relocalization." (PMID 30429226, 2018).
RBM14 also shares sentences with these, for which no sentence is quoted: prostate carcinoma (2 papers); amyotrophic lateral sclerosis (1); Arthritis (1); Ewing sarcoma (1); frontotemporal dementia (1); HCMV infection (1); influenza (1); neurodegenerative disease (1); schizophrenia (1); triple-negative breast carcinoma (1); urothelial carcinoma (1).